TNF (tumor necrosis factor)
Diseases named in the same sentence as TNF in open-access papers (continued):
Sharing a sentence is not in itself a finding about the gene and the disease.
tumor (continued). "The deleterious effect of TNF is confirmed by using both animal models of CRC (ApcMin/+ and AOM/DSS), where abrogation of TNF signaling strongly diminished tumor growth." (PMID 33435303, 2021). "Examples of such tumour-promoting cytokines are IL-6, tumour necrosis factor α (TNF-α) and transforming growth factor β (TGF-β), where several clinical trials targeting these cancer-promoting cytokines are ongoing." (PMID 34830872, 2021). "Anti-tumor activities involve relatively high TNF concentrations and binding to TNFR1, which mediates stromal and tumor cell apoptosis, microvasculature collapse, and increased T and NK cell cytotoxicity, as well as prevents the transition from M1 to M2." (PMID 35048056, 2021). "Their findings obtained from a tumor regression trial showed that the efficiency of the hscFv25-TNF-alpha was more than that of TNF-alpha (3/3 vs. 2/3 remission)." (PMID 34679012, 2021). "Conversely, purified TNF-α treatment resulted in enhanced NF-κB activity and CXCR-4 expression, which further suggests that TNF-α is an important mediator of tumor-infiltrating pDC in the promotion of tumor growth and metastasis." (PMID 33854604, 2021). "The proportion of aldehyde dehydrogenase positive cells (ALDH+) under the overexpression of TNFα in tumor cells was reduced approximately to 50–60% in comparison to parental cells in three engineered cell lines." (PMID 33957885, 2021). "In fact, macrophages produce proinflammatory cytokines, such as TGF-β, IL-6, IL-10, and TNF-α, that induce stem cell-like characteristics in tumor cells, thereby sustaining these tumor cells and allowing them to continue to grow." (PMID 34502312, 2021). "In cancer, TNF-α acts directly to enhance tumor growth and proliferation, stimulating angiogenesis, invasion, metastasis, and DNA damage." (PMID 34287243, 2021). "The nano-drug can also inhibit the expression of TNF-α/IL-1β and reshape the tumor cell TME to enhance the anti-tumor effect and reduce the toxic and side effects caused by drug alone." (PMID 34120620, 2021). "Cells that constitute the tumor stroma provide many factors to initiate and/or support tumorigenesis, including the pro-inflammatory cytokines IL-1β and TNF-α." (PMID 34046348, 2021). "Tumor necrosis factor (TNF) family members participate in the body’s antitumor immunity response and influence tumor prognosis and treatment response." (PMID 34867972, 2021). "The influence of endogenous TNF on lung metastasis has mostly been investigated in mouse models using transplantable tumor cell lines." (PMID 33917839, 2021). "TNF-α, act as an important regulator of the tumor microenvironment, can promote tumor migration and invasion by the TNF-α-NF-κB-Snail pathway (Wu and Zhou, 2010)." (PMID 33510588, 2021). "For example, newly tumor-infiltrated naïve M0 macrophages exert anti-tumorigenic activities via TNFα secretion." (PMID 34201127, 2021). "When secreted by activated CD4+ T-cells, TNFα has been shown to induce myelopoiesis in tumor-bearing mice." (PMID 34445397, 2021). "Our results show that RRx-001 increases RBC adhesion to the endothelium under TNFα induced inflammation and hypoxia, which explain the observed preferential localization to tumor cells." (PMID 33946824, 2021). "Macrophages have two phenotypes, M1 and M2, among which M1 cells are pro-inflammatory cells, producing a variety of inflammatory cytokines, such as IL-6, IL-12, and TNF-α, which play an important role in anti-tumor immunity." (PMID 34721019, 2021). "On day 21 after cryo-thermal therapy, the level of serum TNF-α was significantly lower than that in tumor-bearing control and RFA-treated mice." (PMID 34576115, 2021). "It is well reported that the tumor parenchyma and the TME continuously produce endogenous TNF-α, which induces tumor angiogenesis and promotes progression." (PMID 33986746, 2021).
tumor (continued). "Similar to the caffeine, significant elevation of interferon-γ and tumor necrosis factor-α was observed in the serum and tumor tissues of rats after the theacrine supplement of 50 mg/kg body weight." (PMID 34946538, 2021). "Considering that TNF can also have vascular-damaging effects, we then analyzed the impact of iso1Au/TNF on tumor perfusion using contrast-enhanced ultrasound analysis with microbubbles (CEUS)." (PMID 33952242, 2021). "Meanwhile, IFN-γ, TNF-α, IL-2, and IL-1β play crucial parts in killing tumor cells according to previous researches." (PMID 34721026, 2021). "Expression of the NK cell receptors DNAM-1, CD96 and NKG2D, the degranulation marker CD107a, and the cytokines IFN-γ and TNF, were similar in NK cells derived from tumor bearing B6-MAITcast MR1 WT and B6-MAITcast MR1−/− mice." (PMID 34362900, 2021). "Garcinia livingstonei T. Anderson (GLT) elevates the expression level of iNOS and IL-12, and reduces the expression levels of IL-6, TNF-α, Arg-1, and IL-1β on TAMs to impede the tumor progression through the inhibition of STAT3, JNK, and ERK signaling pathway." (PMID 33748122, 2021). "NK cells are innate lymphoid cells involved in tumor immunosurveillance by inducing cancer cell lysis either directly (via perforin/granzyme system) or indirectly (via secretion of TNFα and IFNγ)." (PMID 34638439, 2021). "This process prompts the release of pro-inflammatory cytokines, including IL-6, IL-12, IFN-γ and TNF-α, to create a delayed type hypersensitivity-like microenvironment that regulates prolonged anti-tumor adaptive responses." (PMID 34322780, 2021). "It has also been shown that tumor necrosis factor α (TNF-α) enhances the release of exosomes by tumor cells." (PMID 34297778, 2021). "Together with cells from the innate and adaptive immune systems and cytokines (e.g., tumor necrosis factor alpha [TNFα] and interleukin [IL]-6), leptin can generate a pro-inflammatory stage in the tumor microenvironment." (PMID 34868066, 2021). "Biglycan acts as a DAMP, and here we provided evidence demonstrating that stromal biglycan promotes TNF-α expression in tumor cells through binding to TLR2 or TLR4, and subsequent activation of NF-κB and ERK signaling pathways." (PMID 33966638, 2021). "For example, TNF can inhibit the transcription of the albumin gene, leading to a low level of albumin in the host, which is conducive to tumor progression." (PMID 33732716, 2021). "Similar changes to cancer immunopeptidomes as a consequence of IFN‐γ and TNF‐α action were observed in other studies and, as a consequence, impacted tumour immunity or cancer immunotherapy." (PMID 34310018, 2021). "TAMs are a population of pro-inflammatory cells that promote tumor progression through cytokines and chemokines like IL-23, IL-6, IL-12, and TNF-α." (PMID 34778068, 2021). "Taken together, ample evidence implicates a dual role of TNF in tumorigenesis depending on the exact mouse model, the experimental context, tumor vs. immune cell origin of the cytokine, and the type of TNF receptor mediating the signal." (PMID 33917839, 2021). "PD1 blockade reinvigorates effector CD8 T cells and these tumor-reactive T cells secrete cytokines, including interferon gamma and tumor necrosis factor alpha (TNFα) and cytolytic enzymes, to kill tumor cells." (PMID 34073253, 2021). "In turn, cytokines secreted by NK cells, such as IFNγ and TNFα as well as NKp30 engagement, support DCs maturation and polarization towards an anti-tumor phenotype." (PMID 34712615, 2021). "TNFα promotes the cytolysis of tumor cells while IFNγ upregulates immunosuppressive molecules to dampen the anti-tumor immune response." (PMID 34869307, 2021).
tumor (continued). "The combined therapy increased the number of tumor-infiltrating IFN-γ/TNF-α-producing CD4 and CD8 T cells and delayed tumor growth, as compared to the effect observed in groups treated with c-di-GMP or IRE alone." (PMID 33575350, 2021). "Previously, we have reported that adaptor proteins like STING and NLRX1 localize to mitochondria and its contact site, which beyond their role in innate immunity, can act as tumor suppressor and modulate mitochondrial functions in the presence of TNF-α." (PMID 33926547, 2021). "The expression of TNF, IFN-γ, GZMA, and GZMB was higher in the low-risk group, suggesting a stronger cytotoxicity to tumor cells." (PMID 34616734, 2021). "Surprisingly, significant elevation of TNF-α level was observed in the serum and tumor tissues of the DMBA-induced rats after daily supplement of a low dosage (50 mg/kg), but not high dosage (100 mg/kg), of theacrine." (PMID 34946538, 2021). "RAE-1γMCMV primed OT-1 cells produced lower amounts of IFNγ, TNFα and IL-2, showed decreased degranulation potential, while simultaneously exhibiting similar cytotoxicity against tumor cells expressing their cognate antigen." (PMID 34168650, 2021). "On the other hand, the heat-inactivated supernatant with either recombinant IFNγ or recombinant TNFα exhibited partial restoration of tumor cell killing activity." (PMID 32666260, 2021). "Several reports have described the secretion of various factors by tumor-infiltrating immune cells, including TNF-α, IL-10, and TGF-β, as impacting the NF-κB pathway." (PMID 33854604, 2021). "The antimetastatic effects of KCs include phagocytosis of tumor cells, apoptosis during the early invasion process, production of the tumor necrosis factor (TNF)-α, and mobilization of neutrophils and NK cells." (PMID 34071550, 2021). "In contrast, myeloid-derived suppressive cells (MDSC), pro-angiogenic Type-2 tumor associated macrophages (TAM) and/or their derivative cytokines IL-6, TNF, IL-1β and IL-23 are generally recognized as dominant tumor-promoters." (PMID 34930302, 2021). "First, in terms of tumor immunotherapy, multiple recombinant influenza viruses expressing tumor necrosis factor and interleukin family members have been established, and they have good therapeutic effects on tumor models." (PMID 33528730, 2021). "Preventing TNFα upregulation of PD-L1 and TIM-3 expression by CD8+ tumor infiltrating lymphocytes (TILs) causes reinvigoration of the antitumor immune response, consequently overcoming anti-PD-1 resistance." (PMID 33540543, 2021). "The fluorescence signal of TNF-α and IL-1β in DOX was most evident, consistent with previous studies that DOX chemotherapy can increase the production of TNF-α and IL-1β and promote the proliferation and metastasis of tumor cells." (PMID 34120620, 2021). "M2-like TAMs are metabolically distinct from M2 macrophages, and utilize glycolysis, while also secreting TNF-α to promote glycolysis in cancer cells, thus facilitating tumor growth." (PMID 33514004, 2021). "In a dose-dependent manner, it inhibited tumor cell proliferation, promoted macrophage proliferation and the expression of TNF- and IL-6 secretion, TLR2 and TLR4, and stimulated macrophage phagocytosis through the release of NO and H2O2." (PMID 33435246, 2021). "Whereas secreted molecules like histamine, IL-4, IL-8, Tumor necrosis factor (TNF-α) contribute in inhibiting tumor cell survival or growth and inducing apoptosis." (PMID 34631562, 2021). "Studies have also found that the tumor necrosis factor is significantly higher in smokers, highlighting tobacco’s key role in influencing tumor status." (PMID 34439379, 2021). "MEG8 and TNF-α are upregulated in tumor tissues of oe-MEG8 group, while miR-454-3p is downregulated." (PMID 34016788, 2021).
tumor (continued). "In vitro studies have demonstrated that reovirus administration induces DC maturation, stimulates proinflammatory cytokine production, including IFN-alpha, TNF-alpha, and IL-6, and increases NK cell cytolytic activity on tumor cells." (PMID 34976006, 2021). "M1 macrophages promote immune response against tumor cells by secretion of inflammatory cytokines with potent antitumor activity such as tumor necrosis factor, while M2 macrophages show an anti-inflammatory function." (PMID 34834304, 2021). "TNF-α is a homotrimeric multifunctional cytokine produced primarily by immune cells (mainly monocytes and macrophages), with both local (e.g. tumor microenvironment) and systemic effects." (PMID 33461943, 2021). "While high-dose exogenous TNFα mainly induces tumor cell apoptosis, endogenous low-concentration TNFα derived from tumor cell or tumor microenvironment contrarily plays an oncogenic role." (PMID 34924562, 2021). "It is worth mentioning that the therapeutic use of IL-2 together with TNF-α has been shown to influence the elimination of the tumour in a mouse model of myeloma, emphasizing the importance of IL-2 in anti-cancer therapy." (PMID 33808304, 2021). "The treatment of CAL-1 cells with tumor supernatant or combination of TGFβ and TNFα prevented TLR9-induced production of type I IFNs." (PMID 33919546, 2021). "MCs through releasing IL-1, IL-4, IL-6, and TNF-α can actively participate in the elimination of tumor cells and rejection of tumors." (PMID 31256327, 2020). "M1-like MDSCs are characterized as tumor-inhibiting cells by the production of TNF-α, IL-12, and nitric oxide, whereas M2-type MDSCs thwart the tumoricidal effect of T lymphocytes or NK cells by secreting TGF-β, IL-10 and arginase." (PMID 32424240, 2020). "As a pro-inflammatory cytokine, TNF is recognized as a key mediator of inflammatory reactions in tumor tissues, and also responsible for increased NF-κB activity in many tumors." (PMID 33109189, 2020). "On the other hand, tumour cells produce TNF-α and IL-1β, which activate pro-angiogenic growth factors to cause enhanced tumour growth." (PMID 32512860, 2020). "Tumor invasion and metastasis augmented by tumor necrosis factor (TNF) and IL-6 were identified as mast cell chemo-attractants." (PMID 32260363, 2020). "In particular, experimental tumor-induced thermal hyperalgesia and nociceptor sensitization were prevented by systemic administration of the anti-TNF drug etanercept." (PMID 32528961, 2020). "As such, changes in inflammatory factors including vascular endothelial growth factor; tumor necrosis factor; and interleukin-1, -6, -8, in the tumor microenvironment facilitate tumor growth and distant metastasis." (PMID 32686760, 2020). "For instance, IL-1 Receptor Associated Kinase-M (IRAK-M) activity is known to be upregulated in tumor-exposed macrophages with significantly high expression in TAMs, which in return, suppresses TNF-α secretion." (PMID 33267818, 2020). "TAMs-derived TNF-α can transport to destination organs, which promote tumor cells recruitment in metastatic foci." (PMID 33201893, 2020). "An analysis of the secretion of cytokines from these cells showed a similar increase in IL6 and TNFα as the tumor progressed." (PMID 33177492, 2020). "Ciji-Hua'ai-Baosheng granules also upregulated the expression of IL-2, IFN-γ, and TNF-α in both serum and tumor tissues in vivo, which can help resist immune-related injuries caused by chemotherapy." (PMID 32595757, 2020). "Tumor cells produce tumor necrosis factor or cytokines that promote coagulation and form microscopic thrombi by inducing disseminated intravascular coagulation." (PMID 32232193, 2020). "Human TNF, which can be considered as a low‐toxic, fast‐cleared mTNF mutant in the mouse, is unable to induce complete tumor regression in the B16Bl6 model, except when combined with mIFN‐γ." (PMID 31912630, 2020).
tumor (continued). "M1 macrophages lead to adipose secretion of several pro-inflammatory cytokines, such as TNF-α, IL-1, and IL-6, contributing to affect the microenvironment of tumor growth." (PMID 31963221, 2020). "In a CAC model, oral pre-treatment with S. gallolyticus exacerbates both inflammation (e.g., IL-6, IL-1β, IL-8, CCL2, TNFα) and tumor formation." (PMID 32962159, 2020). "In fact, the anti‐tumor effects of TNF and IFNγ on activated tumor vasculature are probably the reason why immunotherapy using T cells can destroy solid tumors that are refractory to cytotoxic therapies." (PMID 31916677, 2020). "These cells can induce an immunosuppressive microenvironment and are associated with cytokines such as TNFα, VEGFA, and IL8, and accumulate in hypoxic regions of the tumor." (PMID 33228231, 2020). "Tumoricidal macrophages are critical in promoting tumor killing and apoptosis through the release of cytotoxic factors and also enhance the production of pro inflammatory cytokines, such as IL-1β and TNF-α." (PMID 33036138, 2020). "The effect of the destruction of the tumor vasculature due to the bacterial particles was similar to the combination of six inflammatory cytokines namely, TNF-α, KC, MCP-1, G-CSF, IP-10, and IL-6." (PMID 33066447, 2020). "TNF-α is produced in small quantities (pg) by tumor cells and the tumor microenvironment, and this low level expression is usually associated with poor prognosis." (PMID 32560387, 2020). "AuNPs conjugated to a tumour peptide that binds to CD13 in the tumour endothelium have been shown to transport and release TNF-α more effectively in vivo." (PMID 32610601, 2020). "In the same study, an increase in inflammatory markers such as IL-1β, IL-6, iNOS, and TNFα was also observed in the tumor of voluntary runners." (PMID 33613297, 2020). "In vivo studies, passive immunization against IFNγ and TNF-α of tumor-bearing rats allowed the intake of food, weight preservation, longer life, and better tolerance of larger tumors than in rats receiving a control antibody." (PMID 33158194, 2020). "Although there was a slight difference in the IL-6 and TNF-α mRNA levels, the IL-1β cytokine levels were elevated in tumours injected with IL-33." (PMID 33308251, 2020). "Specific targeting of tumour ECM using the TNFα-CSG fusion compound attracts immune cells into the tumour microenvironment which secrete a cocktail of proteases to degrade ECM, enlarge tumour vessels and increase perfusion." (PMID 32923973, 2020). "At 100 mm3 tumor volume, TAK1KO tumor bearing mice were treated with either TNF (30 μg/kg) 3 times a week or vehicle." (PMID 32523651, 2020). "The anti-tumor activity of tumor necrosis factor alpha gets potentiated by maslinic acid which leads to the inhibition of NF-kappa B signaling pathway." (PMID 32488691, 2020). "Immunohistochemical staining revealed that TNFα is mainly produced by tumor cells, TAMs, endothelial cells, stromal fibroblasts, and inflammatory tumor-infiltrating immune cells." (PMID 33042814, 2020). "The reduced expression of anti-tumour cytokines in CXCL9-treated mice was further proven by the observation that serum level of TNFα, IL2, and IFNγ in CXCL9-treated mice was remarkably suppressed." (PMID 31913856, 2020). "TLR7/8 activation is reported to induce an anti-tumor effect by the release of cytokines such as TNF-α and interleukin-12 and by activation of cytotoxic T lymphocytes." (PMID 32046113, 2020). "During the defense against tumors, immune cells produce pro-inflammatory cytokines such as TNF-α, IL-6, and IL-1β, and tumor-specific T cells produce perforin and granzyme B to clear tumor cells." (PMID 33299138, 2020). "TNF-α has anti-cancer and growth regulatory activities showing selectivity for tumor cells and carrying out pro-angiogenic activity." (PMID 33343362, 2020). "Considering anti-tumor effects of TNFα, number of attempts were made to administer TNFα either systemically or locally in various cancer types." (PMID 32219066, 2020).